MMP9 (matrix metallopeptidase 9)
Diseases named in the same sentence as MMP9 in open-access papers (continued):
Sharing a sentence is not in itself a finding about the gene and the disease.
glioma (continued). "Similarly, we found that the expression of HOXC6, MMP9 and SHOX2 was higher in recurrent glioma tissues compared with primary glioma tissues and the expression of MYOD1 was decreased, while there were no significant changes in WT1 and HOXA2." (PMID 36118887, 2022). "It has been shown that grade III and grade IV glioma patients with no sign of radiographic progression had lower MMP9 levels in their serum than glioma patients with active disease, as well as a transient increase in the serum after resection." (PMID 36400876, 2022). "However, TLR2 upregulated MMP2 and MMP9 expression in GL261 glioma cell lines and promoted tumor invasion, indicating that TLR2 signaling in GSCs is involved in the invasiveness of glioma." (PMID 36611945, 2022). "MMP9 and MUC4 tissue protein expression were significantly correlated with glioma grades." (PMID 36400876, 2022). "This would imply that in the context of glioma, myeloid CD44 regulates both directly and indirectly MMP9 increase, which could explain the observed drastic effect on this proteinase." (PMID 35992852, 2022). "Besides, ursolic acid reduced matrix metallopeptidase 9 (MMP-9) expressions to inhibit metastasis of HeLa, HT1080 (fibrosarcoma) and C6 (glioma) cells." (PMID 35309872, 2022). "This reduction in glioma-derived IL-6, together with altered TLR2 signaling, could concomitantly hinder microglial MMP9 production." (PMID 35992852, 2022). "Furthermore, results analyzed in glioma tissues in the TCGA demonstrated that glioma patients with high expression levels of HOXC6, MMP9 and SHOX2 had lower dis-ease-free survival rates." (PMID 36118887, 2022). "Overall, this could suggest that, like MMP9, MUC4 could be involved in glioma progression as well as in angiogenesis/microvascular proliferation in GBM and could serve as a potential therapeutic target." (PMID 36400876, 2022). "Moreover, increases in expressions of MMP-9 and MMP-2 were indicative of a poor prognosis in glioma." (PMID 35884733, 2022). "Similarly, MMP2 and MMP9 function as the key mediator of VM in glioma, while the suppression of Tenascin‐c attenuates AKT phosphorylation, and downregulates MMP2 and MMP9 expression, thus repressing VM in gliomas." (PMID 34890108, 2022). "Importantly, MMP9 seems to be transcriptionally regulated by EGFR signalling and involved in the regulation of key signalling pathways in glioma, such as PI3K/AKT, STAT3/5, NFkB, ERK, and SHH25–27." (PMID 36400876, 2022). "The current results indicate PTE may inhibit the migration and invasion of glioma cells via downregulation of MMP-2 and MMP-9 accompanied by EMT progression." (PMID 33737656, 2021). "Besides, SLC39A1 promotes the proliferation of glioma cells, inhibits their apoptosis, and promotes the expression of MMP2 & MMP9." (PMID 34615436, 2021). "In addition, the overexpression of LACTB can inhibit the expression of PCNA, MMP2, MMP9 and VEGF, which are believed to play an important role in the proliferation, invasion and angiogenesis of glioma cells." (PMID 33507917, 2021). "Regarding thymol, treatment at concentrations of 100 and 200 μM induced a significant reduction in cell viability and inhibited the migration of glioma cells (C6 cell line) through phosphorylation of PKCα and ERK1/2, that resulted in decreased expression of MMP-9 and MMP-2." (PMID 34305611, 2021). "In this study, CCL2, CCL5, CXCR4, MMP9, and CXCR2 expression was found to be high in TERTmut glioma from all samples and IDHwt subgroups with high levels of neutrophil infiltration, which indicated that N2 phenotype neutrophils were associated with TERT mutation." (PMID 33996815, 2021). "However, more studies are needed to elucidate how MMP-9 and/or MMP-2 directly or indirectly affect glioma cell migration in patients." (PMID 32172480, 2021). "Overall, the present data indicated that PTE may inhibit the migration and invasion of glioma cells via downregulation of MMP-2 and MMP-9 and EMT suppression." (PMID 33737656, 2021).
glioma (continued). "In human GBM, VEGFA, MMP-9, and MMP2 levels correlate with glioma progression and could be secreted by both tumour cells and MDSCs." (PMID 33452462, 2021). "In glioma cells, high expressions of MMP2 and MMP9 suggest an enhanced VM formation ability." (PMID 33542193, 2021). "Knockdown of FOXD2-AS1 in glioma cells significantly inhibited cell proliferation, migration, invasion and epithelial–mesenchymal transition (EMT) and regulated the expression of CDK2, cyclinE1, P21, MMP7 and MMP9." (PMID 33336050, 2020). "Studies have shown that MMP2\MMP9 are zinc-dependent proteolytic enzymes involved in the remodeling and degradation of extracellular matrix (ECM) and can enhance the invasion and metastasis of glioma." (PMID 33292262, 2020). "Then PCNA, MMP-2 and MMP-9 were costained in U251 and T98G cells with immunofluorescence staining assays, the result further showed that unigene56159 silencing suppressed the MMP-2 expression in glioma cells." (PMID 31789416, 2020). "In vitro experimental results show that SLC39A1 promotes the proliferation of glioma cells and inhibits their apoptosis, and may be related to MMP2\MMP9 up-regulation." (PMID 33292262, 2020). "Additionally, EGCG inhibits invasiveness in glioma cells by down-regulating matrix metalloproteinases (MMP-2 and MMP-9) expression, and prevents their proliferation by regulating the MAPK signaling." (PMID 33113890, 2020). "In gliomas, HOTAIR was described to promote invasion through upregulation of MMP-7, MMP-9 and VEGF." (PMID 33375038, 2020). "Similarly, our study finds that SNHG20 is highly expressed in glioma tissues and cells, and knockdown of SNHG20 reduces VM of glioma by reducing the expression of VM-related molecular MMP1, MMP9, VE-Cadherin." (PMID 30744670, 2019). "In glioma tissues, MMP-2 and MMP-9 are the two MMPs most highly expressed." (PMID 31551765, 2019). "To test this possibility, we conducted PLA to determine whether NHE1 is closely located with MMP2, MMP9, or MT1-MMP in glioma cells." (PMID 30262908, 2018). "Furthermore, the effects of GLI2 inhibition on glioma growth were supported by the lower protein levels of ARHGEF16 as well as Ki67 and MMP9 in GLI2A, GANT61 group than in GLI2A, vehicle group, as determined by immunohistochemistry." (PMID 30305138, 2018). "MMP9 has been shown to be predominantly expressed in TAMs in glioma tissues but not the glioma cells." (PMID 30262908, 2018). "For instance, one study showed that urinary MMP-9/NGAL complex was a potential noninvasive biomarker for gastric cancer, while another study found that MMP-9/NGAL activity was a potential biomarker in glioma." (PMID 30262739, 2018). "Recent studies shows tumor necrosis factor-like weak inducer of apoptosis (TWEAK) increases MMP9 expression to promote glioma cell invasion by activating the non-canonical NF-κB signaling pathway." (PMID 30473630, 2018). "MMP-9 and MMP-2 are important matrix metalloproteinases in the migration of glioma cells." (PMID 29062841, 2017). "Furthermore, knockdown of CLC-3 significantly decreased MMP-9 mRNA and protein expression in U87MG and SNB19 glioma cells." (PMID 28969029, 2017). "We observed that the expression of apoptosis-related factors (cleaved caspase 3 and Bad) was lower, while the expression of anti-apoptosis (Bcl2), invasion (MMP2 and MMP9) and chemokine pathway related factors (CXCL10 and CXCR3) was higher in glioma tissues than in normal tissues." (PMID 26506595, 2016). "Lactic acidosis induces production of matrix metalloproteinase-9 (MMP-9) in mouse B16 melanoma, VEGF-A in glioma and glioblastoma cells, and IL-8 expression in pancreatic adenocarcinoma and ovarian carcinoma cells, all making the tumor microenvironment even more complex." (PMID 26909082, 2016). "MMP9 expression was significantly increased in grade IV glioma compared to in grade II and III gliomas (p<0.0001 and p<0.0001, respectively) and was also markedly higher in grade III glioma than in grade II glioma (p<0.0001)." (PMID 27022952, 2016).
glioma (continued). "In our study, we found that blocking the expression of RACK1 greatly inhibited migration and invasion ability of glioma cells, and discovered that knockdown of RACK1 significantly decreased the expression of EMT markers, such as MMP2 and MMP9, ZEB1, N-cadherin, and Integrin-β1." (PMID 27763568, 2016). "It is also well established that miR-203 is down regulated in human glioma and restored expression of miR-203 could negatively regulate migration potential by targeting Robo1/ERK/MMP-9 Signaling cascade." (PMID 27467502, 2016). "MMPs, especially, MMP9 and MMP2 are overexpressed during glioma development." (PMID 27647142, 2016). "Furthermore, NOX4-generated ROS are required for the cycling hypoxia-induced glioma invasion and infiltration through the activation of ERK- and NF-κB-mediated MMP-9 expression." (PMID 27043542, 2016). "Interestingly, we found similar results in our cohort of bevacizumab-treated glioma patients, with an increase of MMP2 and a decrease of MMP9 plasma levels during treatment before progression." (PMID 26921265, 2016). "In this study, the combination of ethanolic extract from propolis and ethanolic extract of fresh-cut H. perforatum L. was proved the ability to reduce invasiveness of glioma cells through the inhibition of MMP2 and MMP9 secretion and suppression of cell migration." (PMID 27647142, 2016). "It is likely that NGAL also promotes glioma progression through its effects on MMP-9; however the specific role of NGAL in glioma tumorigenesis remains unclear." (PMID 26663949, 2015). "In this study, we investigate the effects of TWEAK on noncanonical NF-κB/RelB signaling, MMP9 expression and glioma invasion." (PMID 25622756, 2015). "In addition, EFEMP1 has been shown to be overexpressed concomitantly with MMP-2, MMP-9 and ADAMTS-5 in glioma." (PMID 25987128, 2015). "The result showed that PCNA and MMP9 were also upregulated in glioma tissues compared with non-tumor tissues both at mRNA and protein level." (PMID 26378521, 2015). "In particular, the significance of preoperative and postoperative urine levels of MMP-9/NGAL with respect to clinicopathological features and clinical prognosis of patients with glioma remains unclear." (PMID 26663949, 2015). "Furthermore, a higher percentage of glioma patients was significantly positive for MMP-9, MMP-9/NGAL, and MMP-9 Dimer activity, compared with control patients (p < 0.01)." (PMID 26663949, 2015). "Moreover, in glioma cells, miR-218 was shown to directly target the NF-kB suppressor IKK/Beta, thereby activating the NF-kB pathway and MMP-9." (PMID 24670365, 2014). "In contrast, gelatinase B/MMP-9 optimises non-homologous end joining (NHEJ) DNA repair in human glioma cells." (PMID 24473089, 2014). "Invasion of malignant cells into nearby healthy brain tissue in glioma patients may be mainly mediated by matrix metalloproteinases MMP-2 and MMP-9 which exhibit elevated expression in tumor progression." (PMID 24672773, 2014). "Although AEG-1 has previously been reported to regulate MMP9 expression through c-jun in human glioma cells, we found that AEG-1 does not affect phosphorylation of serines 63 and 73 of c-jun." (PMID 24063540, 2013). "Similar results were also found in glioma, SPARC up-regulated the expression of MMP-2 and MMP-9." (PMID 22879971, 2012). "Among the MMPs, attention in human gliomas has focused on gelatinases (MMP2 and MMP9)." (PMID 22681957, 2012). "Mutating the NF-kappaB binding site in the MMP-9 promoter abrogated luciferase activity, and a MMP-9 promoter fragment lacking the NF-kappaB binding site displayed no significant change in the luciferase activity in Bmi-1 overexpressing glioma cells." (PMID 22967049, 2012). "Interestingly, numerous genes that promote the aggressiveness of glioma, including astrocyte elevated gene-1 (AEG-1), are also involved in the modulation of MMP-9 transcription." (PMID 22967049, 2012).
glioma (continued). "Further, we observed that MMP-9 overexpression does not have much effect on the basal expression of miR-211 in glioma cells but has a significant role in the methylation-mediated silencing of the miR-211 promoter." (PMID 23183822, 2012). "Rapamycin can suppress glioma invasion by blocking the production of MMP-2 and MMP-9." (PMID 22219636, 2011). "The glioma cells showed MMP-2 and MMP-9 gelatinase activities." (PMID 20587068, 2010). "On the other hand, the inverse associations between P2X7R expression and IL-4, IL-8, MMP-9 and PCNA were not in line with previous speculations of P2X7R and glioma promotion." (PMID 41034696, 2025). "Moreover, the complex interplay between MMPs and TIMPs adds another layer of regulatory complexity, where the balance between MMP-9 and TIMP-1 has been shown to influence glioma invasiveness, with higher TIMP-1 levels correlating with reduced MMP-9 activity and, consequently, reduced tumor invasion." (PMID 40265458, 2025). "Furthermore, we found that HSYA inhibited the proliferation, migration, and invasion of glioma U251 cells, and its mechanism may be related to the downregulation of the expression of MMP-2 and MMP-9." (PMID 39877386, 2024). "MMP-9 also functions through a non-canonical mechanism to increase proliferation in glioma." (PMID 37370851, 2023). "According to Western blotting results, TUSC7 overexpression group had significantly lower expressions of MMP2, MMP3 and MMP9 than NC group, whereas they were obviously elevated after silencing TUSC7, suggesting that TUSC7 could inhibit the migration of glioma cells by degrading MMP2, MMP3 and MMP9." (PMID 37100464, 2023). "Importantly, in human glioma microarray specimens (n = 85, N095Ct01, Bioaitech), we found a positive correlation between L1 and MMP2/9 staining intensities in the glioma specimens, thus supporting the notion that MMP2 and MMP9 are involved in L1‐mediated glioma invasion." (PMID 36708044, 2023). "Similarly, miR-98 decreases migration of glioma cells by binding to IKBKE mRNA 3′ UTR to decrease IKBKE expression, decreasing NF-κB p65 subunit nuclear translocation, which decreases expression of matrix metalloproteinase (MMP)-9." (PMID 37370851, 2023). "Additionally, we also evaluated the effect of CBX7 and CBX8 on the invasion ability of glioma cell cells by detecting invasion-related markers of matrix metalloproteinase 2 (MMP2) and MMP9, and further confirmed the corresponding phenotypes of glioma cells by scratch wound-healing assay." (PMID 36034290, 2022). "Another study in glioma cells has shown that TIIA could inhibit viability of cells, their migratory potential and invasiveness, and decrease levels of Cyclin D1, Matrix metallopeptidase 9 (MMP-9) and Vimentin via regulation of miR-16-5p/Talin-1 axis." (PMID 36348403, 2022). "In addition, our findings demonstrated that FOXN3 over-expression triggered an obvious reduction in PCNA, CCND1, MMP9 and Vimentin expression levels in glioma cells, whereas FOXN3 ablation elicited a remarkable elevation in PCNA, CCND1, MMP9 and Vimentin expression levels." (PMID 34511432, 2021). "Overexpression of MMP9 can promote the growth of U87 GBM cells and induce a significant increase in their clonogenicity, suggesting that the MMP9 gene may be involved in the occurrence and disease progression of glioma." (PMID 35154340, 2021). "In gliomas, a downregulation of LACTB leads to an increase in cancer cell proliferation and angiogenesis, corresponding to a poor prognosis in patients, while its overexpression does the opposite by inhibiting PCNA, MMP2, MMP9, and VEGF, which are key regulators in glioma cell proliferation." (PMID 34361072, 2021). "The authors suggest that since PER2 targets the Wnt/β-catenin signaling pathway in GSCs, the downregulation of critical proteins involved in the invasiveness and stemness of GSCs, such as Wnt7b, β-catenin, MMP2, MMP9, and c-Myc, may explain the tumor suppressive role of PER2 in gliomas." (PMID 34361055, 2021).
glioma (continued). "However, in our results, MGMT and MMP-9 did not increase in patients with nonlocal recurrence; we infer that these two mechanisms are not related to the nonlocal recurrence of glioma." (PMID 33585189, 2020). "There has been no report whether FOXK1 regulates transcription of MMP1, MMP9 and VE-Cadherin and regulates the VM formation in glioma." (PMID 30744670, 2019). "Furthermore, silenced ZFAS1 could impair migration and invasion by inhibiting the epithelial–mesenchymal transition through reducing the expression of MMP2, MMP9, N-cadherin, Integrin β1, ZEB1, Twist, and Snail as well as increasing E-cadherin level in glioma." (PMID 29245995, 2017). "In the present study, HDAC1 knockdown significantly increased the expression of BIM, BAX, cleaved CASPASE3 and E-CADHERIN, and suppressed the expression of TWIST1, SNAIL and MMP9, which could be interpreted to be pro-apoptosis and anti-invasion effects of HDAC1 shRNA in glioma cells." (PMID 28624794, 2017). "SMC4 overexpression markedly promoted glioma cell migration and invasive capability in vitro, as well as tumorigenicity in vivo, which was involved in alteration of expression of the invasion-related gene MMP2, MMP9 and the proliferation marker Ki67, but SMC4 downregulation reduced it." (PMID 28287612, 2017). "COL17A1 expression directly affects activated form of Rac expression, indicating that COL17A1 regulate MMP9 expression likely through GTP-Rac1 activity in glioma, Together these data demonstrated that Increased Collagen XVII expression promotes the invasive activities of glioma cells." (PMID 29156757, 2017). "Moreover, Bcl-2 overexpression in glioma, neuroblastoma, melanoma, breast cancer, lung cancer, and vascular smooth muscle cells increases the expression and activity of MMP-2, MMP-9, and uPA." (PMID 26621844, 2016). "TWEAK also promotes noncanonical NFκB-dependent MMP9 expression and glioma cell invasion." (PMID 25622756, 2015). "MMP-9 is detectable in glioma tissues but not in adjacent nontumor tissues." (PMID 26663949, 2015). "The metabolic profiles from cell lines might provide information associated with their malignant features and other biological features; therefore, we further investigated the correlation of these characteristic metabolites with the glioma malignant behavior markers GFAP and MMP-9." (PMID 25163530, 2014). "The increased migratory and invasive ability of Bmi-1-overexpressing glioma cells were dramatically reversed by treatment with JSH-23, a specific NF-kappaB inhibitor that reduces the transcriptional activity of NF-kappaB, and these effects were accompanied by a reduction in MMP-9 expression." (PMID 22967049, 2012). "This study indicated that cathepsin B may be able to regulate the release of MMP-9 and VEGF, suggesting that the inhibition of cathepsin B will also inhibit tumor growth by inhibiting cathepsin B. Angiogenesis has emerged as a therapeutic approach to inhibiting glioma." (PMID 37398678, 2023). "In addition, the MMP-9 expression level was inhibited by both KPF-BBR and KPF-ABR in glioma cells stimulated by 12-O-tetradecanoylphorbol-13-acetate (TPA) and compared with the TPA-treated cells after 72 h of treatment, suggesting that both KPFs had an anti-migratory effect on glioma cells." (PMID 37445894, 2023). "In addition, correlation analysis indicates that SLC39A1 is highly correlated with MMP2\MMP9, suggesting that the up-regulated expression of SLC39A1 may promote the progression of glioma by increasing the intake of zinc ions and increasing the expression level of MMP2\MMP9." (PMID 33292262, 2020). "Moreover, SAA1 inhibition reduced the expression of the metastasis‐related proteins MMP9 and integrin αVβ3 in both GBM cell lines and patients' GBM cultures; neutralizing the secreted form of SAA1 in medium successfully reduced glioma cell migration and invasion." (PMID 29603594, 2018).